GABPB2 (GA binding protein transcription factor subunit beta 2)
Description:
May function as transcription factor capable of interacting with purine rich repeats (GA repeats).
Synonyms: GABPB-2; MGC29891
Tractability: PROTAC: ubiquitination databases record sites on it; its protein half-life has been measured.
Gene: Protein-coding gene on chromosome 1 (151,070,514 to 151,125,542, forward strand). Ensembl gene ENSG00000143458.
Subcellular location: Nucleus
Subcellular location (Human Protein Atlas): Nucleoplasm; Cytosol
Gene Ontology:
Molecular function: protein binding; transcription cis-regulatory region binding; identical protein binding
Biological process: positive regulation of transcription by RNA polymerase II
Cellular component: nucleoplasm; nucleus
Genetic constraint (gnomAD): Loss-of-function variants: 22 observed, 36.87 expected, observed/expected ratio (o/e) 0.6, 90% interval 0.43 to 0.85. The upper end of that interval is the gene's LOEUF score, 0.85, which puts it in group 3 of 6, group 1 being the genes least tolerant of losing a copy. Missense variants: 442 observed, 545.07 expected, observed/expected ratio (o/e) 0.81, 90% interval 0.75 to 0.88. Synonymous variants: 174 observed, 202.43 expected, observed/expected ratio (o/e) 0.86, 90% interval 0.76 to 0.98.
Homologues: Orthologues: chimpanzee GABPB2 (99% identical), macaque GABPB2 (96% identical), pig GABPB2 (91% identical), rabbit GABPB2 (91% identical), guinea pig GABPB2 (88% identical), dog GABPB2 (83% identical), rat Gabpb2 (81% identical), mouse Gabpb2 (78% identical), zebrafish gabpb2b (54% identical), tropical clawed frog gabpb2 (45% identical), Drosophila melanogaster Atac3 (28% identical). Paralogues in human: GABPB1 (60% identical), IQANK1 (19% identical).
Diseases named in the same sentence as GABPB2 in open-access papers:
GABPB2 is named in the same sentence as 8 diseases in open-access papers, as found by Europe PMC text mining. Sharing a sentence is not in itself a finding about the gene and the disease. The quoted sentences say what the papers report.
schizophrenia (1 paper, 2016). A major psychotic disorder characterized by abnormalities in the perception or expression of reality. "However, GABPB2 may be involved in the nuclear control of mitochondrial function which is important to the pathogenesis for schizophrenia." (PMID 28117656, 2016). "GABPB2 has not yet established relationships with schizophrenia." (PMID 28117656, 2016).
GABPB2 also shares sentences with these, for which no sentence is quoted: autoimmune hepatitis (2 papers); glioma (2); pernicious anemia (2); vitiligo (2); CNS tumors (1); Obesity (1); tumor (1).